ABTB1 (ankyrin repeat and BTB domain containing 1)
Description:
May act as a mediator of the PTEN growth-suppressive signaling pathway. May play a role in developmental processes.
Synonyms: BPOZ; PP2259; EF1ABP; Btb3; BTBD21; BPOZ-2
Tractability: Antibody: its Gene Ontology location is reachable by antibodies, with high confidence. PROTAC: ubiquitination databases record sites on it.
Gene: Protein-coding gene on chromosome 3 (127,672,906 to 127,680,926, forward strand). Ensembl gene ENSG00000114626.
Subcellular location: Cytoplasm
Subcellular location (Human Protein Atlas): Cytosol; Nucleoli
Gene Ontology:
Molecular function: protein binding
Cellular component: cytoplasm; cytosol; ubiquitin ligase complex
Genetic constraint (gnomAD): Loss-of-function variants: 45 observed, 57.54 expected, observed/expected ratio (o/e) 0.78, 90% interval 0.62 to 1. The upper end of that interval is the gene's LOEUF score, 1, which puts it in group 4 of 6, group 1 being the genes least tolerant of losing a copy. Missense variants: 630 observed, 667.13 expected, observed/expected ratio (o/e) 0.94, 90% interval 0.88 to 1.01. Synonymous variants: 302 observed, 280.64 expected, observed/expected ratio (o/e) 1.08, 90% interval 0.98 to 1.18.
Homologues: Orthologues: chimpanzee ABTB1 (99% identical), macaque ABTB1 (98% identical), dog ABTB1 (96% identical), mouse Abtb1 (94% identical), guinea pig ABTB1 (93% identical), rat Abtb1 (91% identical), rabbit ABTB1 (91% identical), pig ABTB1 (81% identical), tropical clawed frog abtb1 (71% identical), zebrafish abtb1 (69% identical). Paralogues in human: ABTB2 (18% identical), ABTB3 (18% identical), BTBD2 (16% identical), BTBD3 (16% identical), BTBD6 (16% identical), BTBD1 (15% identical), BTBD9 (15% identical), KLHL11 (10% identical), KBTBD4 (10% identical), SPOPL (9% identical), SPOP (9% identical).
Diseases named in the same sentence as ABTB1 in open-access papers:
ABTB1 is named in the same sentence as 14 diseases in open-access papers, as found by Europe PMC text mining. Sharing a sentence is not in itself a finding about the gene and the disease. The quoted sentences say what the papers report.
colorectal cancer (4 papers, 2020 to 2024). A primary or metastatic malignant neoplasm that affects the colon or rectum. "In colorectal cancer low expression of ABTB1 is associated with suppressed cancer cell proliferation and migration and low expression of miR-4319 targeting ABTB1 is associated with poor prognosis." (PMID 36809527, 2023). "Moreover, the overexpression of miR-4319 markedly reduces colorectal cancer cell proliferation by infecting ankyrin repeat and BTB domain-containing 1 (ABTB1) and alters the cell cycle distribution." (PMID 32571262, 2020).
prostate carcinoma (1 paper, 2023). A carcinoma that arises from epithelial cells of the prostate gland. "Our results suggest that low expression of ABTB1 indicates better progression-free survival and therefore inhibition of ABTB1 may suppress cancer cell proliferation in prostate cancer." (PMID 36809527, 2023).
tumor (3 papers, 2008 to 2017). "In addition, consistent with predicted relationships in this set, experimental studies have demonstrated interactions between the corresponding proteins in neoplasia; for example ABTB1 and EGR2 are mediators of PTEN tumor suppressor function." (PMID 19094230, 2008). "Furthermore, the hub gene of the module in purple was ABTB1 mediating the phosphatase and tensin homolog (PTEN) growth-suppressive signaling pathway, which suppresses tumor cell proliferation and migration." (PMID 29326596, 2017).
ABTB1 also shares sentences with these, for which no sentence is quoted: acute lung injury (1 paper); acute respiratory distress syndrome (1); Alpha-Synucleinopathy (1); cancer (1); COVID-19 (1); infection (1); liver fibrosis (1); Multiple Organ Failure (1); Parkinson disease (1); Sepsis (1); uveal melanoma (1).